ANGPT2 (angiopoietin 2)
Diseases named in the same sentence as ANGPT2 in open-access papers (continued):
Sharing a sentence is not in itself a finding about the gene and the disease.
migraine (1 paper, 2017). "The correlations of VEGF, angiopoietin-2 and thrombopoietin with the age of first ever migraine attack suggest that depletion of proangiogenic factors progresses with the duration of migraine." (PMID 28918499, 2017). "Age of migraine onset correlated with VEGF, angiopoietin-2 and thrombopoietin concentrations." (PMID 28918499, 2017).
Multiple Organ Failure (1 paper, 2018). A progressive condition usually characterized by combined failure of several organs such as the lungs, liver, kidney, along with some clotting mechanisms, usually postinjury or postoperative. "Increased concentrations of endocan and angiopoietin-2 were associated with clinical worsening and progression into specific organ dysfunctions in adult septic patients and as predictors of multiple organ failure." (PMID 30116143, 2018).
myositis (1 paper, 2006). "Analysis of myositis and control muscle tissues also showed a significant up regulation of anti-angiogenic genes (angiopoietin-2, tryptophenyl-tRNA synthetase, interleukin 10 receptor, and TGF-beta) in DM patients suggesting an active ongoing anti-angiogenic response." (PMID 16504012, 2006).
Norrie disease (1 paper, 2023). A rare X-linked genetic vitreoretinal condition characterized by abnormal retinal development with congenital blindness. "A common developmental feature found in a number of rodent models with retinal vascular pathology, such as ROP, Norrie disease, and angiopoietin-2, is a retarded radial vessel outgrowth from the optic disc area during the formation of the superficial vascular plexus." (PMID 37628776, 2023).
onchocerciasis (1 paper, 2009). Onchocerciasis is a form of filariasis, caused by the parasitic worm Onchocerca volvulus, transmitted by the black fly. "The neovascularisation was associated with a particular pattern of angio/lymphangiogenic factors in nodules of onchocerciasis patients, characterized by the expression of CXCL12, CXCR4, VEGF-C, Angiopoietin-1 and Angiopoietin-2." (PMID 20011036, 2009).
parasitemia (1 paper, 2021). "After adjusting for parasitemia, plasma syndecan-1 also correlated with ADMA (r = 0.45, p < 0.001), angiopoietin-2 (r = 0.44, p = 0.002), and ICAM-1 (r = 0.53, p < 0.0001)." (PMID 33963210, 2021).
pituitary tumor (1 paper, 2022). A benign or malignant neoplasm affecting the pituitary gland. "The ANGPT2 protein was also detected in the culture medium of primary pituitary tumor tissue, and its protein levels correlated strongly with their corresponding RNA levels." (PMID 35600354, 2022). "Pituitary tumors also expressed significantly higher levels of angiogenesis growth factors, including VEGFA (4.2-fold), VEGFB (2.2), VEGFC (19.3), PGF (13.4), ANGPT2 (9.2), PDGFA (2.7), PDGFB (10.5) and TGFB1 (3.8) compared to normal pituitary tissue." (PMID 35600354, 2022). "In contrast, expression of ANGPT2 (3.6 x 103 copies/μg total RNA) and TEK (3.4 x 103) was significantly elevated in all types of pituitary tumors with an overall increase of 9.2 (p<0.0001) and 7.3-fold (p<0.0001), respectively." (PMID 35600354, 2022).
prostate tumors (1 paper, 2005). "Finally, in ovarian and prostate tumors, angiopoietin 2 (ANGPT2) measured by PCR was elevated 6-fold (data not shown) versus the 2.2-fold induction found by microarray analysis." (PMID 15836779, 2005).
pulmonary fibrosis (1 paper, 2024). Chronic progressive interstitial lung disorder characterized by the replacement of the lung tissue by connective tissue, leading to progressive dyspnea, respiratory failure, or right heart failure. "Similarly, based on the evaluation of candidate genes identified in genomic analysis, plasma biomarkers extracellular nicotinamide phosphoribosyl transferase (eNAMPT) and angiopoietin-2 (ANG-2) have also been associated with complicated phenotypes and pulmonary fibrosis." (PMID 38337432, 2024).
retinal degeneration (1 paper, 2018). Degeneration of the retina. "In hyperoxia, which in short-term promotes astrocyte differentiation, in long-term causes retinal degeneration and paradoxically can cause hypoxia by blocking vascular development in the retina, Angpt1 mRNA expression was decreased while Angpt2 and Angpt4 mRNA levels increased." (PMID 30444491, 2018).
retinal ischemia (1 paper, 2025). A ischemic disease that involves the retina. "Catalpol’s unique action on multiple angiogenic pathways, including β-catenin, HIF-1α, VEGF, and angiopoietin-2, and on inflammatory biomarkers (i.e., MCP-1) suggests that these mechanisms may play key roles in treating retinal ischemia." (PMID 40362263, 2025).
retinoblastoma (1 paper, 2017). A malignant tumor that originates in the nuclear layer of the retina. "After comprehensive study, they found that MMP-2 and -9 are involved in stimulating cell migration and contributing to cell viability whereas MMP-9 played an additional role in Angiopoietin-2 production thus enhancing angiogenesis in retinoblastoma cells." (PMID 29233192, 2017).
retinopathy of prematurity (1 paper, 2015). A bilateral retinopathy characterized by neovascularization, scarring, retinal detachment, and eventually blindness. "Exaggerated secretion of VEGF, Epo, Angiopoietin-2, and metabolic factors like succinate is responsible for the excessive growth of retinal blood vessels toward vitreous and lens during retinopathy of prematurity (ROP)." (PMID 26194913, 2015).
rosacea (1 paper, 2025). A chronic erythematous skin disorder that affects the face. "In this study we explored the expression of Angiopoietin 1, Angiopoietin 2, and Tie2 by immunohistochemistry in rosacea lesions." (PMID 41562711, 2025). "In this study we found in rosacea skin elevated levels of the proteins Angiopoietin 2 and Tie2, which are involved in blood vessel growth and behavior." (PMID 41562711, 2025). "Angiopoietin 2, other than VEGF, has been shown to be significantly upregulated in rosacea lesions." (PMID 41562711, 2025). "Significantly increased expression of Tie2 and Angiopoietin 2 in the endothelial cells of the dermal vessels in rosacea skin vs. non-lesional skin (100% and 33.3% for Tie2, and 100% and 50% for Angiopoietin 2) was observed." (PMID 41562711, 2025). "An anti-malarial drug, Artemisinin, decreased the expression of Angiopoietin 2 and VEGFC, but not VEGFA or VEGFB, in a mouse model of rosacea induced by LL37, the proinflammatory form of cathelicidin, and showed a beneficial clinical effect in rosacea patients." (PMID 41562711, 2025).
scleroderma (1 paper, 2024). Scleroderma is a rare autoimmune connective tissue disorder characterized by abnormal hardening of the skin and, sometimes, other organs. "Angiopoietin-2 showed a weak correlation with a scleroderma pattern." (PMID 39242108, 2024).
sickle cell disease (1 paper, 2018). Sickle cell anemias are chronic hemolytic diseases that may induce three types of acute accidents: severe anemia, severe bacterial infections, and ischemic vasoocclusive accidents (VOA) caused by sickle-shaped red blood cells obstructing small blood vessels and capillaries. "The study provides a first report on plasma levels of angiopoietin-1, angiopoietin-2, and vascular endothelial growth factors in homozygous sickle cell disease patients in Ghana." (PMID 29954157, 2018). "The study provides a first report on plasma levels of angiopoietin-1, angiopoietin-2, and vascular endothelial growth factors, as well as Ang-2/Ang-1 ratios, in homozygous sickle cell disease patients in Ghana." (PMID 29954157, 2018).
skin cancer (1 paper, 2024). "For example, impaired tumor vascularization of skin cancer xenografts, as determined by altered blood vessel morphology and decreased expression of proangiogenic factors (VEGF, placental growth factor (PlGF), angiopoietin-2), has been shown in nude mice treated with the CB2 receptor agonist JWH-133." (PMID 38255884, 2024).
skin toxicity (1 paper, 2019). "We found that ANGPT2 rs1961222 and rs17063434 were associated with late skin toxicity with grade ≥ 2 (Common Terminology Criteria for Adverse Events (CTCAE) 4.0) (p = 0.030 and p = 0.003, respectively)." (PMID 31330833, 2019). "We also investigated the relationship between ANGPT2 and NOS3 polymorphisms and the main toxicities (skin toxicity, asthenia, and diarrhea)." (PMID 31330833, 2019).
spontaneous abortion (1 paper, 2025). Expulsion of the product of FERTILIZATION before completing the term of GESTATION and without deliberate interference. "In additional, abnormal ANGPT2 levels are associated with spontaneous abortion.In this study, ANGPTA2 levels increased in the EPL group, indicating that high levels of ANGPTA2 are adverse to pregnancy, which is consistent with these findings." (PMID 38773024, 2025).
squamous cell carcinoma (1 paper, 2020). A carcinoma arising from squamous epithelial cells. "The specific roles of VEGFA and ANGPT2 in adenocarcinoma (ADC) and squamous cell carcinoma (SQC) are still not fully understood." (PMID 31892982, 2020).
steatosis (1 paper, 2021). Increased lipid within the cytoplasm of cells. "In contrast with our results of VAT-ANGPT2 being downregulated in patients with NAFLD, a study of 93 severely obese subjects found that ANGPT2 expression in VAT was associated with different NAFLD features, including steatosis, ballooning, portal and lobular inflammation." (PMID 34638880, 2021).
Sturge-Weber syndrome (1 paper, 2023). Sturge-Weber syndrome (SWS) is a rare congenital neurocutaneous disorder characterized by facial capillary malformations and/or cerebral and ocular ipsilateral vascular malformations that result in variable degrees of ocular and neurological anomalies. "Interestingly, GNAQ mutations drive constitutively active PLCB3 which increases ANGPT2—as a corollary, blocking ANGPT2 normalized enlarged vessels suggesting a potential treatment approach for Sturge-Weber syndrome." (PMID 37060495, 2023).
Systemic capillary leak syndrome (1 paper, 2016). Systemic capillary leak syndrome (SCLS) is a severe systemic disease due to increased capillary permeability, characterized by episodes of hypotension, edema and hypovolemia. "Although the implication of vascular endothelial growth factor, angiopoietin-2, and C-X-C motif chemokine 10 has been suggested, the pathogenesis of systemic capillary leak syndrome remains unclear." (PMID 27386947, 2016).
Tetralogy of Fallot (1 paper, 2023). A congenital cardiac malformation comprising pulmonary stenosis, overriding aorta, ventricular septum defect, and right ventricular hypertrophy. "In a large cohort of individuals with tetralogy of Fallot, there was no increased burden of rare variants in ANGPT2 (K Devriendt, MD, personal communication, December 2020)." (PMID 34876502, 2023).
thyroid tumor (1 paper, 2015). A benign or malignant neoplasm affecting the thyroid gland. "The overexpression of angiopoietin-2 and VEGF was shown in thyroid tumor progression, such as a strong association between tumor size and high levels of VEGF and angiopoietin-2." (PMID 25789503, 2015).
triple-negative breast carcinoma (1 paper, 2021). An invasive breast carcinoma which is negative for expression of estrogen receptor (ER), progesterone receptor (PR), and human epidermal growth factor receptor 2 (HER2). "A single dose of bevacizumab reduced the density of angiopoietin-2-positive vessels while improving the infiltration of CD4+ T and CD8+ T cells, and mature dendritic cells in patients with primary triple-negative breast cancer." (PMID 34188163, 2021).
ulcer (1 paper, 2025). "They found that factors such as disease perception, ulcer duration, and biochemical markers (e.g., IL-6, microRNA-146a-5p, PECAM-1, and angiopoietin-2) had substantial predictive value for healing outcomes." (PMID 40620799, 2025).
tumor (365 papers, 2003 to 2026). "ANGPT2 is mainly produced by endothelial cells and is expressed at low levels in normal tissues but is usually highly upregulated in the tumor-associated vasculature." (PMID 41602344, 2026). "In epithelial ovarian cancer (EOC), tumor-associated macrophages promote angiogenesis via IGF-I secretion in response to angiopoietin-2 (Ang2), highlighting IGF1 as a potential therapeutic target." (PMID 41463024, 2025). "YAP and TAZ play central roles in angiogenesis by inducing VEGF and other pro-angiogenic mediators, such as Angiopoietin-2 (Ang-2), thereby supporting both physiological and tumor-associated neovascularization." (PMID 41028521, 2025). "The interaction between VEGF and the angiopoietin-2 (Ang-2)/Tie signalling system promotes the dissolution of the basement membrane by proteases, thereby increasing the “leakiness” of tumor-associated blood vessels." (PMID 37631236, 2023). "EC-derived angiopoietin 2 (Ang-2) supports tumor progression by inducing Tie2, the Ang-2 surface receptor, which is involved in the recruitment of tumor-associated macrophages and monocytes." (PMID 36901858, 2023). "Silencing Arid1a gene in murine hepatocellular carcinoma (HCC) cells increases blood vessel density in the tumor by inducing expression of Ang2, a gene encoding angiogenic factor angiopoietin 2 (ANG2)." (PMID 38017409, 2023). "We investigated the expression of HRAGs in HCC tumor tissues, and their associations with survival, and constructed a novel prognostic model based on three HRAGs (ANGPT2, SERPINE1, and SPP1) to stratify HCC patients according to their estimated survival." (PMID 36110938, 2022). "It has been well-known that ANGPT2 expression is biologically linked to angiogenesis and metastasis of tumor cells and play an important role in cancer progression." (PMID 35987690, 2022). "ANGPT2, which belongs to the angiopoietin family, is highly expressed in diverse tumor cells, and is implicated in tumor angiogenesis and inflammation." (PMID 36110938, 2022). "High circulating levels of ANGPT2 have been observed in various human cancers, where they associate with aggressive tumor behaviors and poor prognosis." (PMID 35266635, 2022). "TIE2+ TAMs are closely associated with tumor vasculature and have been found crucial for angiogenesis, which depends on angiopoietin-2 (Ang2), a TIE2 ligand produced by endothelial cells." (PMID 33802565, 2021). "Our results demonstrate associations between Angpt2 rs1823375 and rs12674822 polymorphisms and risk of CRC; our evidence shows a significant association between Angpt2 rs12674822 and tumor site in a Han Chinese cohort." (PMID 31929743, 2020). "Increased ANGPT-2 expression has been observed in activated endothelial cells during inflammation and in tumor-associated vessels of several human cancers in response to hypoxia and VEGF." (PMID 31690961, 2020). "Previous study has indicated that the expression of VEGFA in tumor cells was positively associated with ANGPT2 and predicted poor survival." (PMID 31892982, 2020). "Angpt1 has several well-known anti-inflammatory properties while Angpt2 is pro-inflammatory and has been shown to activate Tek-positive tumor associated macrophages." (PMID 28800750, 2017). "Angpt1 has several well-known anti-inflammatory properties and Angpt2 has been shown to activate Tek-positive tumor associated macrophages." (PMID 28800750, 2017). "Its infection causes tumour-like angiomatous lesions on the patients’ skin through the expression of two angiogenic factors, angiopoietin-2 and VEGF28." (PMID 26728351, 2016). "Herein, we demonstrate that estrogen-deficient BM niche overexpresses angiopoietin-2, which negates ER+ tumor cell dormancy and eventually promotes estrogen-independent tumor growth." (PMID 27353038, 2016). "Angiopoietin-2 and Follistatin protein levels within the tumor tissue were associated with tumor type (p = 0.022 and p = 0.001)." (PMID 25885021, 2015).
tumor (continued). "Angiogenic factors were associated with the following clinicopathological factors: tumor tissue expression of Angiopoietin-2 and Follistatin was higher in SCC compared to AEG (p = 0.022 and p = 0.001)." (PMID 25885021, 2015). "Angiopoietin-2 regulates tumour angiogenesis, and increased levels of tumour Ang-2 are associated with more aggressive, angiogenic CRC tumours." (PMID 21081932, 2011). "Additionally, we observed a trend in the levels of angiopoietin-2 and tumor grade; as tumor grade increased, the levels of angiopoietin-2 increased, indicating an association with tumor progression and aggressiveness." (PMID 39511039, 2024). "Thus, Angpt2 is a partial agonist of tumor‐associated Tie2 and causes its phosphorylation and then the activation of Fak and Erk1/2, as previously demonstrated in ECs." (PMID 35266635, 2022). "The high levels of TGF-β1 and angiopoietin-2 were both associated with severe tumor stages and metastasis, indicating that they could be used as a reliable prognostic biomarkers panel for CCA patients." (PMID 33806004, 2021). "In addition, targeting ANGPT2 has been shown to elicit significant suppression of angiogenesis, normalize tumor-associated vessels, and inhibit metastasis." (PMID 34577576, 2021). "Furthermore, the treatment of ANGPT2-blocking antibodies was shown to suppress tumor-associated lymphangiogenesis and promote endothelial cell–cell junctions." (PMID 33172072, 2020). "TAMs are one of at least four myeloid subpopulations derived from tumor-associated myeloid cells (TAMCs) that also include myeloid-derived suppressor cells (MDSCs), tumor-associated neutrophils (TANs), and angiogenic monocytes expressing angiopoietin-2 (TIE-2)." (PMID 33381449, 2020). "In contrast, the overexpression of angiopoietin-2 (Ang-2) was associated with an advanced disease state and poor prognosis in different solid malignancies, thus suggesting differential roles of Ang-1 and Ang-2 in tumour biology." (PMID 30042823, 2018). "Furthermore, ANGPT2 expression in ER+ tumor human samples was associated with increased risk of distant metastasis only in those who underwent adjuvant estrogen depletion therapy, not in those who did not undergo adjuvant therapy." (PMID 27353038, 2016). "In our preliminary study, plasma levels of ANGPT2 and TuM2PK obtained prior to ablation or surgery for renal masses, were increased compared to controls and were associated with several aggressive pathological features including tumor size and grade." (PMID 25885592, 2015). "Moreover, in the RIP1-Tag2 pancreatic islet carcinoma model, angiopoietin-2 (ANG2) has been found to regulate the biological characteristics of endothelial cells by binding to TIE2 expressed by tumor-associated macrophages (TEMs), thereby promoting angiogenesis and vascular remodeling." (PMID 41158622, 2025). "To summarize, overexpression of ANGPT2 in ESCA is associated with an unfavorable prognosis and compromised tumor immunity." (PMID 41823527, 2026). "Angiopoietin-2 (ANG2), associated with tumor angiogenesis, has been shown to outperform AFP in predicting overall survival (OS) in HCC." (PMID 40269686, 2025). "Tumor hypoxia upregulates the expression of the TIE2 receptor on the TME and the production of angiopoietin-2 (ANG-2) in tumor endothelial cells (TECs)." (PMID 40438141, 2025). "The VEGF proteins in combination with angiopoietin-2 also synergistically drive tumor vascularization and growth." (PMID 40072060, 2025).